STAT3 (signal transducer and activator of transcription 3)
Diseases named in the same sentence as STAT3 in open-access papers (continued):
Sharing a sentence is not in itself a finding about the gene and the disease.
cancer (continued). "It has been shown that matrine can interact with the Src kinase structural domain to inhibit Src activity and downregulate MAPK/ERK, JAK2/STAT3, and PI3K/AKT phosphorylation signaling pathways, thereby inhibiting the proliferation of cancer cells." (PMID 38279206, 2024). "Overall, our study reveals a mechanism by which STAT3 remains activated in NSCLC and provides a new target for cancer therapeutic approaches." (PMID 38760429, 2024). "Human cancers overexpress c-MYC in 70% of cases, due to alterations in signal transduction pathways, such as STAT3 pathway, or due to genomic aberrations, such as amplifications and translocations." (PMID 39769907, 2024). "Many of these genes such as those in the NF-κb, STAT3, and YAP pathways, have been shown to drive breast cell transformation and cancer metastasis." (PMID 39041189, 2024). "Activation of the JAK2/STAT3 pathway increases BCa cell growth, promotes EMT, and thereby, invasion and migration of cancer cells, cancer cell stemness and chemoresistance." (PMID 39040042, 2024). "These cytokines contribute to the proliferation and migration of cancer cells via the activation of MAPK/ERK, JAK2/STAT3, and PI3K/AKT signaling pathways." (PMID 39220365, 2024). "IL-6 transduction signaling mechanisms activate various pathological pathways, such as JAK/STAT3, Ras/MAPK, and PI3K-PKB/Akt, and regulate CD4+T cell and VEGF levels, leading to cancer, inflammatory diseases, and neurological diseases." (PMID 38645489, 2024). "Apigenin, Chrysin, and Fisetin are flavonoids that inhibit the NF-κB, STAT3, and PI3K/AKT pathways, leading to reduced cancer cell proliferation and enhanced apoptosis." (PMID 39650709, 2024). "The crosstalk between the JAK/STAT pathway and other pathways, such as the formation of complexes between STAT3/SMAD3 and STAT3/CD44, contributes to the generation of cancer stem cells." (PMID 38553760, 2024). "Presently, mounting evidence suggests that UBE2S impacts cancer progression through multiple mechanisms, such as NF-κB, Cell cycle, SOX6-Catenin, Wnt/β-catenin, PI3K/AKT/mTOR, PTEN-AKT, and VHL/HIF-1α/STAT3." (PMID 38312603, 2024). "We also Meanwhile, this study proved that the downregulation of LINC01929 significantly inhibited cancer cell growth and induced cell cycle arrest potentially through modulation of the TNF signalling pathway and its downstream STAT3." (PMID 39586790, 2024). "Comparatively, TOPK emerges as a superior target for cancer therapy compared to other direct downstream molecules of ALK, including Smad4, STAT3, PI3K, and PLC-γ." (PMID 38397899, 2024). "The LIF/STAT3/FGFR4 axis can serve as survival mechanism to promote the growth of neoplastic cells and development of cancer cells chemoresistance." (PMID 37945798, 2024). "STAT3 and STAT5 are two members of the STAT protein family that are the most frequently activated in cancers and can drive cancer pathogenesis directly." (PMID 38611065, 2024). "Non-responder-specific gene signatures were regulated by Activator Of Transcription 3 (STAT3) and Nuclear Factor Kappa B Subunit 1 (NFKB1), known to play roles in PD-L1 regulation and T cell activation in cancer." (PMID 39514276, 2024). "ICAM-1 participates in cell migration and proliferation via NFκB, NPM1, Pho/JNK, GTP/LFA-1/JAK/STAT3, and Ras/RAF/MEK/ERK activates the Raf/MEK/ERK pathway which is responsible for cancer cell proliferation and migration." (PMID 39149564, 2024). "There is mounting evidence that miRNAs play an important role in cancer etiology, notably in the modulation of the Janus kinase/signal transducer and activator of transcription 3 (JAK/STAT3) signaling pathway in malignancies." (PMID 38511067, 2024).
cancer (continued). "In a feedback loop, the polarized macrophages secreted IL-6, which further activated STAT3 signaling in UBC cells, thus maintaining cancer stemness." (PMID 39479456, 2024). "Oncogenic transcription factors such as STAT3 and STAT5, which sit at convergence points of multiple upstream pathways, are appealing targets for cancer therapy." (PMID 38611065, 2024). "In this study, we have demonstrated that exosomal miR-320d promotes cancer cell metastasis and enhances angiogenesis by downregulating GNAI1 expression and enhancing JAK2/STAT3." (PMID 39695099, 2024). "Mechanistically, this enhancer is bound by the key transcriptional regulator STAT3 and promotes ETV4 expression, ultimately leading to cancer-related phenotypes." (PMID 38849954, 2024). "They contribute to cancer cell proliferation by activating the RAS, STAT3, and PI3K/AKT pathways, respectively." (PMID 38796445, 2024). "B7H4 promotes a more aggressive phenotype in cancer cells and silences antitumour responses in OSCC via PD-L/STAT3 signalling, thus making it an attractive target for OSCC therapy." (PMID 39061159, 2024). "Lately, some evidences have suggested that various transcription factors, such as JAK2/STAT3, NF-kB, PI3K/AKT/mTOR and MEK1/2/ERK1/2 facilitate the transcription of PD-L1 in cancer." (PMID 38326861, 2024). "Signal transducer and activator of transcription 3 (STAT3), as a transcription factor, regulates a series of genes related to cancer cell survival, proliferation, angiogenesis, invasion, and metastasis." (PMID 39179991, 2024). "LINC00518 influences cancer through multiple mechanisms, including lncRNA-miRNA-mRNA ceRNA networks and activation of JAK/STAT3, Wnt/β-catenin, Integrin β3/FAK, and MAPK signaling pathways." (PMID 39108268, 2024). "The IL6/STAT3 axis also increases TDO2, and consequent KYN production leads to the activation of AhR in response to inflammation in various types of cancer." (PMID 39311710, 2024). "The suppression of STAT-3, p38, and ERK1/2 phosphorylation, combined with the modulation of pro-apoptotic protein expression, is supposed to trigger the anti-cancer properties of delphinidin in CRC." (PMID 39335919, 2024). "Our previous studies demonstrated that SH003 treatment induces apoptotic and autophagic cell death of cancer cell lines by targeting PI3K-Akt signaling pathway and their downstream signaling including STAT3 and mTOR." (PMID 38303001, 2024). "Polyphenolic compounds primarily modulate PD-L1 expression by inhibiting key signaling pathways (IFN-γ-induced STAT1, STAT3, JAK2/STAT1, EGFR/Akt, and NF-κB), potentially enhancing the immune system’s capacity to target and eradicate cancer cells." (PMID 38594256, 2024). "It is worth noting that among these genes, STAT3 is the known cancer driver gene, while SHC1 and GRB2 are cancer driver genes predicted by SGCD (ranked in the top 50 predicted cancer driver genes of MULTINET)." (PMID 39751645, 2024). "Cancer cells’ ability to survive, migrate, and invade their surroundings is greatly influenced by the FAK/STAT3 signaling mechanism." (PMID 39588118, 2024). "The aberrant activation of the IL6/GP130/STAT3 signaling pathway and the IL6 feed‐forward loop formation are the drivers of tumorigenesis in many types of cancer, including NSCLC." (PMID 39152779, 2024). "Treatment of these cancer cells with simvastatin reduced LDL-induced proliferation, cell mobility, and STAT3 activation." (PMID 38464736, 2024). "A previous study from our laboratory uncovered a novel link between STAT3 and cancer showing that activation of STAT3 in KRAS mutant cancers led to the stabilization of epithelial differentiation." (PMID 38573819, 2024).
cancer (continued). "Signal Transducer and Activator of Transcription 3 (STAT3) is a pleiotropic transcription factor playing essential roles in normal development, immunity, response to stress/damage and cancer." (PMID 38150153, 2024). "In melanoma, highly activated STAT3 and STAT5, along with a potential role of G6PD in cancer mediated by these STAT proteins, has been observed." (PMID 39796677, 2024). "Curcumin was first reported to control the activated STAT3 by affecting the expressions of PIAS and JAK/STAT suppressor genes in cancer." (PMID 38590645, 2024). "We investigated the role of the IL-6-induced GP130/JAK2/STAT3 pathway in the proliferation, migration, and EMT of KSCs, as these properties are known to promote cell metastasis in cancer." (PMID 38519574, 2024). "The STAT5, STAT3, and JAK2 signaling pathways play an important role in inhibiting the growth and differentiation of cancer cells." (PMID 39063337, 2024). "With respect to the tumor microenvironment, it has been shown that cancer-associated fibroblasts and pro-tumorigenic macrophages secrete IL-6 that triggers STAT3 activation in CRC cells, and this leads to an increase in RAC1B expression in the cancer cells." (PMID 39001533, 2024). "Multitude of cancer-related signaling cascades like Wnt-β-catenin, PI3K/AKT, ERK, VEGF, NF-κB, STAT3 and gonadal hormone signaling pathways are tightly modulated by TBL1XR1." (PMID 38347836, 2024). "HDAC3 regulates PD-L1 expression at the transcriptional level through various transcriptional factors, including STAT3, bromodomain containing 4 (BRD4), and p65, while further inhibiting the STAT3 cascade in cancer cells." (PMID 39690423, 2024). "Specifically, in cancer cells, RELA and STAT3 physically interact, thereby integrating the NF-κB and JAK/STAT signaling pathways." (PMID 39435663, 2024). "The IL-6/STAT3 signaling pathway and TYRO3 collectively involve cancer cell survival, proliferation, and resistance to chemotherapeutic agents." (PMID 38431573, 2024). "Signal transducer and activator of transcription 3 (STAT3), a component of the Janus kinase (JAK)-STAT signaling pathway, is well-known for its role in driving immune evasion in various cancer types." (PMID 39034990, 2024). "Here, we show that those NFs, isolated from HNSCC patients, results from the cancer cells-mediated activation of STAT3, which regulates MMP1 expression that are subsequently utilized by the cancer cells." (PMID 38320998, 2024). "The abnormal activation of multiple signal transduction pathways, such as the JAK/STAT3, PI3K/AKT, and MAPK/ERK pathways, promotes cancer cell proliferation and metastasis." (PMID 39684626, 2024). "Several crucial transcription factors, including STAT3, HOXD9, and HOXB5, are known to bind to ANGPT2 promoter regions, thereby activating ANGPT2 expression and promoting malignant phenotypes in cancer cells 58-60." (PMID 39309430, 2024). "In this context, Cheng Wei and collaborators described a positive feedback loop between cancer cells and TAMs involving the IL6/STAT3 pathway, with a critical role in cancer progression and metastasis." (PMID 38391950, 2024). "Despite the potential of STAT3 inhibitors in PDAC based on preclinical studies, many trials investigating STAT3 inhibitors in many cancers have failed." (PMID 38464736, 2024). "STAT3 is a crucial player of the JAK/STAT pathway and its activation is related to inflammation, malignant tumors and autoimmune illnesses." (PMID 38495094, 2024). "Melatonin enhances the anti-cancer effects of sorafenib by suppressing the PDGFR-β/STAT3 signaling pathway and activating melatonin receptors (MT) to inhibit STAT3." (PMID 38474109, 2024).
cancer (continued). "These cytokines participate in angiogenesis and play an executive role in cancer cell proliferation and metastasis by controlling NF-κB, IL-6/JAK/STAT3, PI3K-PKB/Akt, Ras/Raf, JNK, MAPK, and AKT pathways." (PMID 39664179, 2024). "It has been demonstrated that GM-CSF from cancer cells triggers STAT3 activation in TAMs, while SHP2 is capable of counteracting STAT3's activity." (PMID 38747738, 2024). "Based on available data, STAT3 and STAT5, two of the seven members of the STAT protein family, are crucial for advancing cancer." (PMID 38397437, 2024). "Therefore, targeting STAT3 could effectively suppress cancer." (PMID 39590337, 2024). "For example, although activation of STAT3 and STAT5 is a poor prognostic factor in many cancers, in other types, it can be favorable." (PMID 39405604, 2024). "STAT3 and STAT5 promote the expression of pro-survival and pro-growth genes and are constitutively active in various cancers." (PMID 39796677, 2024). "PDLIM2 has been demonstrated to regulate different signaling pathways, including NF-κB, STAT3, NOS2, TGF-β/Smad, and β-catenin in cancer cells." (PMID 38880883, 2024). "Although small, these differences affected important signaling pathways (NGF-stimulated transcription, IL-10 signaling, PERK activity) and cancer genes (CBFA2T3, ETV4, FGFR1, GLI1, SGK1, and STAT3)." (PMID 38968069, 2024). "The regulation of cellular pathways, transcription factors, and cytokines, including IL-6/STAT3, SNAIL, TWIST, and zinc finger E-box-binding (ZEB), plays a pivotal role in the metastatic process of cancer." (PMID 38543002, 2024). "For instance, in pathways related to cancer, a previous study highlighted that the prolonged inflammation characteristic of IBD triggers activation of the JAK/STAT3 pathway." (PMID 39273699, 2024). "The binding of miR-483 with NEAT1 increased STAT1, STAT3 and other EMT markers in U2O3 cells and greatly helped in EMT and metastasis of cancer cells." (PMID 40176927, 2024). "In various types of cancers, SEs control the expression of prominent tumor-promoting genes such as MYC, TAL1, STAT3 and EGFR, and mediate transcription dysregulation of cancer cells." (PMID 38254188, 2024). "We further revealed that inhibitors targeting the Src, Mcl‐1, STAT3, BRD4, p300, PLK1, or class I HDACs significantly enhanced CDK9i‐induced cell death in various KRAS‐mutant cancers." (PMID 39254172, 2024). "Our results unveiled the molecular mechanisms of metochalcone against carcinomas, which are dependent on the JAK2/STAT3 signaling axis to induce SASP." (PMID 38686052, 2024). "In different cancer models, Arc suppressed EGFR- and Her2-mediated signaling cascades, Akt/mTOR-, and STAT3/β-catenin-dependent pathways." (PMID 38001865, 2023). "Administering this compound significantly repressed STAT3 R729me2a, STAT3 Y705 phosphorylation, cancer cell metastasis, and ultimately extended the overall survival of mice harboring MDA-MB-468 cancer cell xenografts." (PMID 37813837, 2023). "Our data demonstrated the synergistic inducing EMT effect of IL-6 combined with hypoxia via the IL-6/STAT3/HIF-1α autocrine loop, which contributes to understanding cancer progression and invasiveness, and developing a feasible therapeutic strategies for EOC." (PMID 36814597, 2023). "Pathways in cancer: intrinsic and extrinsic processes connect cancer with inflammation, activating transcription factors including NFKB, STAT-3, and HIF-1." (PMID 37109422, 2023). "IL-17 promotes cancer progression by activating multiple signaling pathways, including JAK/STAT3, MAPK, PI3K/Akt, and NF-κB." (PMID 37894738, 2023). "In response to hypoxia in cancer cells, HIF-1 increases the expression of JAK2 and STAT3, activating the JAK–STAT pathway and its downstream signaling pathways." (PMID 37373133, 2023).
cancer (continued). "MDSCs influence CSC biology through three IL-6-dependent phosphorylation of STAT3 and nitric oxide (NO)-mediated NOTCH signaling pathways which maintain continuous and potent IL-6/STAT3 activation and impact cancer stemness." (PMID 38090567, 2023). "In cancer cells, JAK/STAT signaling can be activated by multiple mechanisms, most notably by STAT3 activation." (PMID 38140103, 2023). "The second subnetwork containing 13 nodes and 12 edges showed the interaction between PRDX2 and TAGLN2 as well as a mild increase in multiple components of the peroxisome (SOD1, CAT, PRDX5, PRDX1) and proteoglycans in cancer (FLNA, STAT3)." (PMID 38322285, 2023). "Curcumin decreased the high glucose-induced survival of cancer cells upon doxorubicin and methotrexate treatment, suppressed glucose uptake, lactate production, expression of GLUT1/3, MCT1/4, HIF1α, mTOR, STAT3, and multidrug resistance protein MDR-1." (PMID 38001865, 2023). "Because of this, the effects IL-6 has on cancer cells of CAC and other forms of colorectal cancer are likely mediated by STAT3." (PMID 38002302, 2023). "Signal transducer and activator of transcription 3 (STAT3) is a transcription factor involved in multiple fundamental biological processes and a key player in cancer development and progression." (PMID 37097001, 2023). "The expressions of signal transducers and activators of transcription 3 (STAT3), vascular endothelial growth factor (VEGF), and hypoxia-inducible factor-1α (HIF-1α) in cancer cells were examined by immunostaining and analyzed by the Image J analysis system." (PMID 37333486, 2023). "Here, we show that STAT3 positively regulates the activities of Pol III-dependent transcription and cancer cell growth." (PMID 36656267, 2023). "The other pathways of upregulation in multiple cancer types are allograft rejection (n = 28), IL‐6/JAK/STAT3 signalling (n = 24), inflammatory response (n = 23), ROS pathway (n = 22) and TNF‐α signalling through NF‐kB (n = 14)." (PMID 37097039, 2023). "The specific pathways targeted by miRNAs are mediated by the key players in cancer development and proliferation, including HIF-1 alpha, PI3K/Akt, and STAT3 signaling, which play critical roles in the prognosis and survival of BCSCs." (PMID 38132441, 2023). "Inhibition of IL-6/STAT3 prevents atrophy in the SOD1 transgenic mice and in cancer cachexia models." (PMID 37828541, 2023). "The activation of STAT3 correlated with the increased expression of ALDH1, CD44, OCT4, and SOX2 in cancer cells." (PMID 37453969, 2023). "Among the STAT family members, STAT3 and STAT5 are involved in cancer progression (especially STAT3)." (PMID 37375411, 2023). "In addition, miR-145 may suppress STAT3 activation in cancer." (PMID 37834058, 2023). "JAK/STAT3 is one of the important signaling pathways that play pivotal roles in the regulation of cell proliferation, EMT process, cancer stem cell properties, metastasis, and chemoresistance in a variety type of cancer." (PMID 36217054, 2023). "In the present study, we found that the STAT3 signaling pathway played an important role in mediating the function of IL20RB in promoting cancer stemness and chemoresistance, and IL20RB-STAT3 signaling promoted the expression of NANOG, SOX2 and POU5F1." (PMID 38098005, 2023). "The signaling pathways in various cancers were PI3K, AKT, mTOR, MAPK, ERK, JAK, STAT3, EGFR, AMPK, ERK1/2, S473AKT, Ras, ErbB2/ErbB3, JNK1/2." (PMID 37743502, 2023). "Butein is known to exhibit anticancer effects by the inhibition of STAT3, Akt, and PI3K signaling in other cancers as well." (PMID 37047012, 2023). "Studies of cancer cells and ex vivo–stimulated T cells detail how cross-regulation between STAT1 and STAT3 modulates target gene expression." (PMID 37272871, 2023). "STAT3, a member of the signal transducer and activator of the transcription (STAT) family, is an oncogene that plays a crucial role in cancer initiation and progression." (PMID 37612721, 2023).